MRPL4 (mitochondrial ribosomal protein L4)
Synonyms: L4mt; CGI-28; uL4m
Tractability: Small molecule: a structure with a bound ligand is known. PROTAC: ubiquitination databases record sites on it; its protein half-life has been measured.
Gene: Protein-coding gene on chromosome 19 (10,251,901 to 10,260,060, forward strand). Ensembl gene ENSG00000105364.
Subcellular location: Mitochondrion
Pathways (Reactome):
Metabolism of proteins: Mitochondrial ribosome-associated quality control; Mitochondrial translation elongation; Mitochondrial translation initiation; Mitochondrial translation termination
Gene Ontology:
Molecular function: protein binding; RNA binding; structural constituent of ribosome
Biological process: mitochondrial translation; positive regulation of Notch signaling pathway; regulation of translation; translation
Cellular component: mitochondrial large ribosomal subunit; mitochondrion; mitochondrial inner membrane; ribosome
Genetic constraint (gnomAD): Loss-of-function variants: 33 observed, 35.7 expected, observed/expected ratio (o/e) 0.92, 90% interval 0.7 to 1.24. The upper end of that interval is the gene's LOEUF score, 1.24, which puts it in group 5 of 6, group 1 being the genes least tolerant of losing a copy. Missense variants: 401 observed, 437.59 expected, observed/expected ratio (o/e) 0.92, 90% interval 0.84 to 1. Synonymous variants: 196 observed, 193.27 expected, observed/expected ratio (o/e) 1.01, 90% interval 0.9 to 1.14.
Homologues: Orthologues: macaque MRPL4 (90% identical), chimpanzee MRPL4 (82% identical), guinea pig MRPL4 (80% identical), pig MRPL4 (79% identical), rat Mrpl4 (78% identical), dog MRPL4 (77% identical), mouse Mrpl4 (77% identical), zebrafish mrpl4 (59% identical), tropical clawed frog mrpl4 (56% identical), Drosophila melanogaster mRpL4 (43% identical), Caenorhabditis elegans mrpl-4 (39% identical).
Diseases named in the same sentence as MRPL4 in open-access papers:
MRPL4 is named in the same sentence as 15 diseases in open-access papers, as found by Europe PMC text mining. Sharing a sentence is not in itself a finding about the gene and the disease. The quoted sentences say what the papers report.
allergic rhinitis (3 papers, 2011 to 2015). Inflammation of the nasal mucous membranes caused by an IgE-mediated response to external allergens. "Previous reports revealed that several genetic variants of candidate genes, such as ADAM33, IL4, MRPL4, and TNFA, are positively associated with susceptibility to allergic rhinitis." (PMID 26177022, 2015). "Our study suggests that MRPL4 and BCAP, key components of the HIF-1α and PI3K/Akt signaling pathways respectively, are two novel candidate genes for atopy and allergic rhinitis." (PMID 21625490, 2011). "Hence the study of polymorphisms in MRPL4, BCAP and other molecules involved in the HIF-1α and PI3K/Akt signaling pathways might help understand how they are regulated and in turn shed light on the pathophysiology of allergic rhinitis and other atopic phenotypes." (PMID 21625490, 2011). "Hence the study of MRPL4, BCAP other molecules involved in the HIF-1α and PI3K/Akt signaling pathways might help understand the pathophysiology of allergic rhinitis and other atopic phenotypes." (PMID 21625490, 2011).
Hypertension (2 papers, 2022). The presence of chronic increased pressure in the systemic arterial system. "Some studies have indicated that the MRPL4 gene can be a potential therapeutic target for the treatment of hypertension and stroke." (PMID 36035311, 2022). "Recently, it has been seen that Mrpl4 plays important role for development of hypertension and stroke in rats." (PMID 36394275, 2022).
prostate carcinoma (2 papers, 2024 to 2025). A carcinoma that arises from epithelial cells of the prostate gland. "One of the most promising prognostic targets of cancer metastasis is MRPL4, with studies consistently demonstrating that increased expression is associated with a higher risk of metastasis in both breast and prostate cancer." (PMID 39354291, 2024). "Interestingly, expression of MRPL4 was found to have a greater association with high-risk samples than AMACR, an established biomarker of prostate cancer, with MRPL4 overexpression also associated with increased mortality and poorer survival." (PMID 39354291, 2024). "In prostate cancer, comparison of expression between benign prostatic hyperplasia and low- and high-risk primary prostate cancer samples, revealed 56 proteins, including MRPL4, which were highly expressed in the high-risk samples compared to the other two groups." (PMID 39354291, 2024).
benign prostatic hyperplasia (1 paper, 2024). A non-cancerous nodular enlargement of the prostate gland. "MRPL4 gene expression in high-risk samples was also more than double that of low-risk and benign prostatic hyperplasia samples." (PMID 39354291, 2024).
breast carcinoma (1 paper, 2024). "(2017) observed, through an informatics-based approach, that MRPL4 expression was associated with tumour recurrence and hormone resistance in breast cancer, further suggesting a role in aggressive cancer phenotypes." (PMID 39354291, 2024). "Microarray data from 3,951 breast cancer tumours additionally revealed that increased expression of MRPL4 was associated with distant metastasis in estrogen-receptor positive patients." (PMID 39354291, 2024).
osteosarcoma (1 paper, 2025). A usually aggressive malignant bone-forming mesenchymal neoplasm, predominantly affecting adolescents and young adults. "It was shown that MRPL4 showed higher expression in samples of high-grade osteosarcoma than in mesenchymal stem cells (MSCs) as a normal control." (PMID 40989695, 2025).
ovarian carcinoma (1 paper, 2025). A malignant neoplasm originating from the surface ovarian epithelium. "We found that the expression of BANF1, CDK2AP2, DDT, LRIG1, MRPL4, and S100A13 was upregulated in ovarian cancer samples, and the expression of EPS8, NUCB2, PAF1, PMP22, RABGAP1L, and USO1 was upregulated in normal samples." (PMID 41000388, 2025).
tumor (5 papers, 2019 to 2025). "The high expression of MRPL4 in OS samples, especially in metastatic samples, suggests that it may promote tumor invasiveness by enhancing mitochondrial metabolic activity and energy supply." (PMID 40989695, 2025). "The mitochondrial metabolic pathway regulates mitochondrial ribosomal protein synthesis through MRPL4, MRPL58, and TSFM, enhances mitochondrial oxidative phosphorylation capacity, and provides continuous energy for tumor cells." (PMID 40989695, 2025). "The expressions of DVL1, MRPL4, and NSUN3 were relatively higher, while that of RPH3A was relatively lower in the tumor tissues." (PMID 36035311, 2022). "The analysis revealed that in the training set, the expression of BANF1, CDK2AP2, DDT, LRIG1, MRPL4, and S100A13 was significantly upregulated in tumor samples, and the expression of EPS8, NUCB2, PAF1, PMP22, RABGAP1L, and USO1 was higher in control samples (p < 0.05)." (PMID 41000388, 2025).
MRPL4 also shares sentences with these, for which no sentence is quoted: cancer (2 papers); Stroke (2); COVID-19 (1); Crohn disease (1); lung carcinoma (1); myocardial ischemia (1); psoriasis (1).